MIR4510 (microRNA 4510)
Synonyms: hsa-mir-4510; mir-4510
Gene: MicroRNA gene on chromosome 15 (35,926,856 to 35,926,923, forward strand). Ensembl gene ENSG00000265098.
Homologues: Orthologues: chimpanzee MIR4510 (100% identical).